ENSG00000251818
Synonyms: LOC124900402
Gene: Small Cajal body-specific RNA gene on chromosome 17 (28,018,770 to 28,018,907, forward strand). Ensembl gene ENSG00000251818.
Gene Ontology:
Biological process: RNA processing
Cellular component: Cajal body; nucleolus
Homologues: Paralogues in human: SCARNA20 (72% identical).